ATP7A (ATPase copper transporting alpha)
Diseases named in the same sentence as ATP7A in open-access papers (continued):
Sharing a sentence is not in itself a finding about the gene and the disease.
iron deficiency (7 papers, 2012 to 2022). "It was noted that an enterocyte copper transporter, copper-transporting ATPase 1 (Atp7a), was strongly induced during iron deficiency in rats and mice." (PMID 27537180, 2016). "A more recent study suggests that HIF2α-dependent upregulation of Atp7a during iron deficiency/hypoxia also requires the transcription factor, Sp1." (PMID 25835049, 2015). "Upregulation of Atp7a is thus consistent with documented alterations in intestinal and body copper levels during iron deficiency." (PMID 23776592, 2013). "Moreover, Sp1 itself binds ATP7A promoter in human intestinal epithelial cells being fundamental for the HIF2α-mediated induction of gene transcription during iron deficiency/hypoxia to regulate iron balance." (PMID 30530920, 2018). "Moreover, iron deficiency in mice leads to up-regulation of copper absorption genes (Atp7a and Mt1)." (PMID 25835049, 2015). "We thus aimed to test the hypothesis that Atp7a function is important for the copper-related compensatory response of the intestinal epithelium to iron deficiency." (PMID 23776592, 2013). "Given its’ necessity for assimilation of dietary copper, Atp7a may mediate increases in body copper levels during iron deficiency." (PMID 23776592, 2013). "Recent results have shown that ATP7A is upregulated by the transcription factor hypoxia inducible factor (HIF2alpha) in response to iron deficiency in rat intestinal epithelia, which could also be the case in the brain." (PMID 23055972, 2012). "The effect of iron deficiency on copper export and ATP7A might be attributed to increased transcription levels." (PMID 23055972, 2012). "Intestinal copper transporter (Atp7a) mutant-brindled mice with systemic Cu deficiency had elevated Cu levels in enterocyte cells without any perturbation of iron-regulating genes, suggesting that blood Cu level might be important for intestinal iron homeostasis during iron deficiency (ID)." (PMID 36494833, 2022). "In response to iron deficiency, the expression of DMT1 mRNA as well as the dedicated copper transporters ATOX1 and ATP7A is upregulated, whereas there is no change in the expression levels of Ctr1." (PMID 23055972, 2012). "The same regulatory picture is seen in vivo in duodenum, where the expression of DMT1 and ATP7A, but not of Ctr1 or ATP7B, is strongly induced in rat duodenum in response to dietary iron deficiency; significantly higher liver-copper levels were additionally observed." (PMID 23055972, 2012).
colon cancer (6 papers, 2005 to 2025). "At the same time, elesclomol has been shown to degrade copper-transporting ATPase 1 (ATP7A) in colon cancer cells, a protein responsible for intracellular export of copper." (PMID 41198664, 2025). "Meanwhile, the use of elesclomol has been reported to degrade copper-transporting ATPase 1 (ATP7A) in colon cancer cells, a protein that mediates intracellular copper export." (PMID 36089608, 2022). "Copper metabolism has a vital role in tumorigenesis and elesclomol, as a copper chelator, could inhibit colon cancer cells by targeting ATP7A and regulating ferroptosis." (PMID 36146640, 2022). "Surgically resected ATP7A positive human colon tumor cells were significantly resistant to SN-38 than ATP7A negative cells ex vivo." (PMID 26988911, 2016).
melanoma (6 papers, 2003 to 2025). A malignant, usually aggressive tumor composed of atypical, neoplastic melanocytes. "(2013) showed that depletion of strumpellin from MNT‐1 melanoma cells caused a missorting of BLOC‐1 cargoes ATP7A and VAMP7 to the plasma membrane." (PMID 27390154, 2016). "Melanoma cells express ATP7A and CTR1 to regulate copper transport and the efficiency of electron transport through cytochrome c oxidase." (PMID 41463339, 2025). "Melanoma cells produce exosomes that contain S100A4, ATP7A, and MET mRNA that modify the calcium homeostasis of astrocytes and copper metabolism, thereby supporting angiogenic remodeling." (PMID 41463339, 2025).
diabetes (5 papers, 2014 to 2024). "Notably, Sudhahar V observed a significantly reduced expression of ATP7A in the vasculature of diabetic mice, and a decrease in ATP7A expression in extracellular vesicles of patients with diabetes and animal models was discovered by Abdelsaid K, which could be partially restored through exercise." (PMID 38904034, 2024). "Further investigation of the deep links between ATP7A/ATP7B and diabetes should be conducted to provide a deeper understanding of the development of this condition." (PMID 38904034, 2024). "To date, only the ATP7A protein is markedly downregulated in vessels isolated from T2DM patients and diabetic mice, whereas how the other copper transporters, ATP7B and SLC31A1, change in diabetes was uncertain." (PMID 36675183, 2023). "Thus, it is possible that ATP7A downregulation in diabetes may contribute to decreased VEGFR2 expression via inducing autophagy, leading to impaired angiogenesis in diabetic peripheral arterial disease." (PMID 34035268, 2021). "Furthermore, diabetes depressed levels of additional intracellular copper-transporting proteins, including antioxidant-protein-1 (ATOX1) and copper-transporting-ATPase-2 (ATP7B), whereas TETA elevated copper-transporting-ATPase-1 (ATP7A)." (PMID 24927960, 2014).
distal spinal muscular atrophy (5 papers, 2012 to 2024). "Recently, two missense mutations in the ATP7A gene were shown to cause X-linked distal spinal muscular atrophy type 3 (SMAX3; OMIM 300489), a degenerative neuromuscular disorder that typically affects patients in the second or third decade of life." (PMID 22900086, 2012).
glioma (5 papers, 2022 to 2026). A benign or malignant brain and spinal cord tumor that arises from glial cells (astrocytes, oligodendrocytes, ependymal cells). "In conclusion, the results suggest that the expression patterns and clinical significance of ATP7A and ATP7B in glioma differ: high ATP7A expression is associated with poor prognosis, while ATP7B downregulation also predicts poor clinical outcomes." (PMID 41463095, 2025). "Furthermore, the expression patterns of ATP7A and ATP7B significantly affect the prognosis of glioma: high expression of ATP7A is associated with poor clinical prognosis, while low expression of ATP7B is also associated with poor prognosis." (PMID 41463095, 2025). "ATP7A expression positively correlated with BMAL1 expression in patients with IDH-WT GBM in the Chinese Glioma Genome Atlas (CGGA)." (PMID 41480765, 2026). "ATP7A is highly expressed in glioma tissues, and patients with high expression of ATP7A have a lower survival rate." (PMID 41463095, 2025). "To further explore the clinical significance of ATP7A in glioma and its relationship with TRIM14, we first conducted an analysis using public databases." (PMID 41463095, 2025). "Such a reduction in ATP7A-mediated copper transport would be expected to enhance intracellular copper retention and sensitize glioma cells to copper-dependent cytotoxicity." (PMID 41463095, 2025). "Results from the TCGA dataset show that ATP7A expression is significantly higher in glioma tissues compared to normal brain tissue." (PMID 41463095, 2025). "We found that high expression of TRIM14 may enhance glioma cell resistance by promoting the upregulation of ATP7A, reducing copper accumulation, and inhibiting cuproptosis." (PMID 41463095, 2025). "Furthermore, Cox regression analysis in the TCGA database showed that FDX1, LIPT1, DLD, DLAT, SLC31A1, ATP7A, and DLST might be risk factors; however, LIAS, ATP7B, and GCSH were significant preventive factors for gliomas." (PMID 37515314, 2023). "This study aimed to investigate the role of tripartite motif-containing protein 14 (TRIM14) and its downstream effector ATP7A in mediating TMZ- and copper-induced cuproptosis in glioma." (PMID 41463095, 2025). "The expression of GLS (p < 0.001), LIPT1, FDX1, SLC31A1 (p < 0.01), DLST, CDKN2A, PDHA1, ATP7A, ATP7B, and NFE2L2 (p < 0.05) was different between glioma and adjacent tissues." (PMID 36936439, 2023). "Further mechanistic studies suggest that TRIM14 may regulate ATP7A protein levels through interaction, highlighting the potential role of the TRIM14–ATP7A axis in copper homeostasis and glioma progression." (PMID 41463095, 2025). "For example, downregulating TRIM14 expression may enhance the antitumor effects of TMZ+CuCl2 co-treatment in gliomas, while avoiding TRIM14′s promotion of resistance through the maintenance of high ATP7A expression." (PMID 41463095, 2025). "In patient samples, ATP7A was elevated in isocitrate dehydrogenase-WT (IDH-WT) and 1p/19q–non-codeleted gliomas, increased with tumor grade, and correlated with poor prognosis." (PMID 41480765, 2026).
liver cancer (5 papers, 2022 to 2024). An epithelial or non-epithelial malignant neoplasm that arises from the liver. "It will be interesting to investigate whether there is liver cancer-related mutation in ATP7A gene and if so, whether this mutation will affect cuproptosis and liver cancer development." (PMID 36033443, 2022). "Experiments on liver cancer have demonstrated elevated expression of ATP7A in liver cancer samples." (PMID 38200525, 2024). "Expression of the Cu transporter genes ATP7A, ATP7B, SLC31A1 and SLC31A2 were found significantly altered in liver cancer samples with elevated Cu levels." (PMID 37324184, 2023). "Cu transporter-related genes such as ATP7A, ATP7B, and SLC31A1 were singularly expressed or copied in liver cancer samples and a relative higher level of Cu was observed in HCC cell." (PMID 36438201, 2022).
Parkinson disease (5 papers, 2017 to 2025). A progressive degenerative disorder of the central nervous system characterized by loss of dopamine producing neurons in the substantia nigra and the presence of Lewy bodies in the substantia nigra and locus coeruleus. "Further examination of the interactions of Atp7a and Snca in Parkinson’s disease, as well as other neurodegenerative diseases, is merited." (PMID 40678754, 2025). "We controlled the expression of ATP7A in adult dopaminergic neurons, a group of cells frequently used to model Parkinson’s disease in Drosophila." (PMID 28355134, 2017). "In contrast, in the comparison between stage IV and V Parkinson’s disease patients, probably due to the small sample size, only ATP7A was significantly different in the two groups (p < 0.05), suggesting what seems to indicate their potential role in Parkinson’s onset and progression." (PMID 36338988, 2022). "Our results identified three characteristic cuprotosis-related genes ATP7A, SLC31A1, and DBT involved in the immune process of Parkinson’s disease." (PMID 36338988, 2022).
esophageal squamous cell carcinoma (4 papers, 2022 to 2023). Esophageal squamous cell carcinoma (ESCC) is a type of esophageal carcinoma (EC) that can affect any part of the esophagus, but is usually located in the upper or middle third. "Increased expression of ATP7A correlates with platinum resistance in esophageal squamous cell cancer." (PMID 37007145, 2023). "Copper-transporting ATPase 1 (ATP7A) is highly expressed in esophageal squamous cell carcinoma and is correlated with tumorigenesis and cisplatin resistance." (PMID 36979661, 2023). "In the research of esophageal squamous cell cancer, researchers found out that the ATP7A knockdown by siRNA partially reversed resistance, and may provide novel strategies to overcome platinum drug resistance." (PMID 35265524, 2022).
Intellectual disability (4 papers, 2016 to 2025).
X-linked distal hereditary motor neuropathy (4 papers, 2020 to 2026). X-linked form of distal hereditary motor neuropathy. "We have generated induced pluripotent stem cell (iPSC)-derived motor neurons from a patient with the p.T994I ATP7A gene mutation as an in vitro model for X-linked dHMN (dHMNX)." (PMID 31969342, 2020). "Furthermore, mutations in the copper transport gene ATP7A cause, among another two distinct human diseases, X-linked distal hereditary motor neuropathy, a condition that affects ATP7A intracellular trafficking and alters Cu levels within the nervous system." (PMID 35892326, 2022).
amyotrophic lateral sclerosis (3 papers, 2020 to 2025). Amyotrophic lateral sclerosis (ALS) is a neurodegenerative disease characterized by progressive muscular paralysis reflecting degeneration of motor neurons in the primary motor cortex, corticospinal tracts, brainstem and spinal cord. "A 65 year old male presenting with brachial amyotrophic diplegia and diagnosed with amyotrophic lateral sclerosis (ALS) was found to harbor a p.Met1311Val (M1311V) substitution variant in ATP7A." (PMID 33359139, 2021).
atherosclerosis (3 papers, 2015 to 2024). A disease characterized by the build-up of fatty material and calcium deposition in the arterial wall resulting in partial or complete occlusion of the arterial lumen. "It provides insight into ATP7A as a novel therapeutic target for vascular remodeling and atherosclerosis." (PMID 37324184, 2023). "In the training dataset GSE97210, SLC31A1, ATP7A, SLC31A2, UBE2D1, CP and FDX1 were highly expressed while LOXL2, COA6 and SOD1 were lowly expressed in the atherosclerosis group as showed in the bar charts." (PMID 37324184, 2023).
bladder cancer (3 papers, 2016 to 2024). "After compiling the data, we would like to first point out that suppressing the expression of the efflux transporters ABCB1, ABCC2, SLC25A21, and ATP7A has been linked to cisplatin’s accumulation and reduced resistance in urinary bladder cancer patients." (PMID 36650399, 2023). "We concluded that the efflux transporters ABCB1, ABCC2, SLC25A21, ATP7A, and the uptake transporter OCT2, as well as the organic anion uptake transporters OAT1 and OAT2, are linked to cisplatin accumulation, toxicity, and resistance in urinary bladder cancer patients." (PMID 36650399, 2023). "When bladder cancer cell lines RT4 and T24 were treated with large doses of cisplatin, both ATP7A and ATP7B expression levels were significantly reduced, while CTR1 gene activity remained unaltered." (PMID 36650399, 2023). "We measured the mRNA expressions of MDR1, MRP1, MRP2, ABCG2, CTR1, ATP7A, and ATP7B in T24 and J82 bladder cancer cells in different groups." (PMID 27485374, 2016). "In the present study, we investigated the expressions of MDR1, MRP1, MRP2, CTR1, ATP7A, ATP7B, and ABCG2 in T24 and J82 bladder cancer cells treated with emodin and cisplatin alone or in combination." (PMID 27485374, 2016).
cervical cancer (3 papers, 2019 to 2024). A primary or metastatic malignant neoplasm involving the cervix. "In summary, we report a new antitumor mechanism by which triptolide disrupted intracellular copper homeostasis and induced cuproptosis in cervical cancer by regulating the XIAP/COMMD1/ATP7A/B axis." (PMID 39198750, 2024). "In summary, we report a new antitumor mechanism of triptolide, which disrupted intracellular copper homeostasis and induced cuproptosis in cervical cancer cells by regulating the XIAP/COMMD1/ATP7A/B axis." (PMID 39198750, 2024). "In our previous studies, we have also shown that the expression levels of ATP7A are significantly higher in cervical cancer cells resistant to platinum drugs than in parenteral cells." (PMID 31450627, 2019). "We demonstrated that triptolide upregulated COMMD1 expression and downregulated ATP7A and ATP7B expression by inhibiting XIAP, thereby promoting intracellular copper accumulation and subsequently inducing cuproptosis in cervical cancer cells." (PMID 39198750, 2024). "However, when the cells were treated with PTX, this drug induced the downregulation of the ATP7A, ATP7B, CTR1, MRP-2, and GSR genes in both cervical cancer cell lines." (PMID 33680921, 2020).
hepatocellular carcinoma (3 papers, 2015 to 2024). A malignant tumor that arises from hepatocytes. "The up-regulation of ATP7A that we revealed in these hepatoma cell lines is intriguing." (PMID 26438057, 2015). "In CRCs and hepatocellular carcinoma (HCC), elevated levels of copper transport ATPase (ATP7A) mRNA have also been observed." (PMID 38994937, 2024).
Hypertension (3 papers, 2013 to 2024). The presence of chronic increased pressure in the systemic arterial system. "It has been demonstrated that ATP7A, a copper-transporting protein, plays a critical role in Ang II-induced hypertension and the regulation of endothelial function by modulating SOD3 activity and vascular superoxide anion production." (PMID 39267854, 2024). "Conversely, in norepinephrine-induced hypertension, the generation of vascular oxygen anions was unaffected in ATP7A mutant mice with impaired copper transport, a finding consistent with observations in SOD3 knockout mice." (PMID 39267854, 2024). "Therefore, Atox1 and ATP7A likely play significant roles in hypertension by regulating both kidney and brain functions." (PMID 39267854, 2024). "Loss of ATP7A function in mice worsens angiotensin-2 induced hypertension by reducing SOD3 activity and increasing vascular superoxide thus demonstrating an essential role for ATP7A in vascular homeostasis." (PMID 34068984, 2021).
lymph node metastasis (3 papers, 2022 to 2024). "ATP7A (P = 0.007), LIPT1 (P = 0.009), DLAT (P = 0.006) and NDOR1 (P = 0.039) expression were remarkably interrelated to lymph node metastasis (N classification)." (PMID 36313717, 2022).
muscular atrophy (3 papers, 2013 to 2021). The loss of muscle tissue due to inactivity or disease. "Recently, a novel ATP7A-related disease phenotype was discovered, spinal muscular atrophy, distal, X-linked 3 (SMAX3), which is characterized by atrophy of the lower limb muscles." (PMID 24904274, 2014). "Recently, missense mutations in ATP7A were found to cause a form of dHMN, which represents the third clinical phenotype associated with mutations in ATP7A. dHMNs are a clinically and genetically heterogeneous group of diseases characterized by lower-motor neuron weakness and muscular atrophy." (PMID 23986700, 2013).
non-small cell lung carcinoma (3 papers, 2012 to 2022). A group of at least three distinct histological types of lung cancer, including non-small cell squamous cell carcinoma, adenocarcinoma, and large cell carcinoma. "ATP7A is upregulated in gemcitabine-resistant non-small cell lung cancer." (PMID 36568224, 2022). "ATP7A expression may thus be a predictive biomarker of chemoresistance and a negative prognostic factor for survival in non-small cell lung cancer (NSCLC) and ovarian cancer patients treated with platinum-based chemotherapy." (PMID 33271772, 2020).
pancreatic cancer (3 papers, 2018 to 2025). "Concerning the ATP7A protein, it is also deregulated in many cancers, such as in pancreatic cancer, where ATP7A is upregulated compared to that in chronic pancreatitis." (PMID 33271772, 2020).
renal fibrosis (3 papers, 2023 to 2026). A final common manifestation of a wide variety of chronic kidney diseases characterized by glomerulosclerosis and tubulointerstitial fibrosis. "(b) Overexpression of ATP7A caused an elevation of copper ions within the Golgi apparatus, resulting in increased LOX activity and enhanced ECM crosslinking, thereby promoting the progression of renal fibrosis." (PMID 42100872, 2026).
Salmonella Infections (3 papers, 2013 to 2021). Infections with bacteria of the genus SALMONELLA. "Achard and co-workers showed that LPS and Salmonella infection increase the expression of genes responsible for copper uptake (Ctr1) and cellular copper redistribution (Atp7a) in macrophages." (PMID 34571908, 2021). "Atp7a mRNA and protein expression was robustly up-regulated by LPS and IFNγ in RAW264.7 mouse macrophages, and Salmonella infection also increased Atp7a mRNA levels in primary mouse macrophages." (PMID 23738776, 2013).